TLR4 (toll like receptor 4)
Diseases named in the same sentence as TLR4 in open-access papers (continued):
Sharing a sentence is not in itself a finding about the gene and the disease.
bacterial infection (continued). "LPS was used to stimulate TLR4, mimicking bacterial infection." (PMID 41255761, 2025). "In addition, TLR4 is induced by DM conditions in many cell types, not only in response to bacterial infections, such as LPS stimulation." (PMID 41369400, 2025). "The present study further confirms the critical role of TLR4 in viral and bacterial infections." (PMID 40572089, 2025). "Recent study demonstrated that bacterial infection could trigger assembly of the complex of mechanical sensor Piezo1 and Toll‐like receptor‐4 (TLR4), and then augment phagocytosis, mitochondrion‐phagosomal ROS production in macrophage." (PMID 38973085, 2024). "Studies have shown that TLR4 plays a crucial role in the immune response to bacterial infections." (PMID 39466745, 2024). "Tlr2 and Tlr4 play essential roles in signal transduction in bacterial infection." (PMID 38711507, 2024). "In this report, PBMCs were challenged with PolyI:C to simulate a strong viral infection (via TLR3) and LPS to simulate a strong bacterial infection (via TLR4) to better understand the impact of being overweight and heavy drinking on interferon and cytokine responses." (PMID 37361874, 2023). "Thus, our study also provides a paradigm of microglial activation in response to bacterial infection via TLR4 and the NF-κB signaling pathway." (PMID 35742984, 2022). "Thus, the appropriate threshold level for TLR4 activation is beneficial to anti-bacterial infection." (PMID 35370674, 2022). "Without functional TLR4, both human or mouse are more susceptible to pathogenic bacterial infection." (PMID 35370674, 2022). "Particularly, the major innate immune response TLR4 pathway in bacterial infection was enriched." (PMID 35288544, 2022). "TLR4, an important component of the innate immune system, is a germline‐encoded pattern‐recognition receptor (PRR) responsible for the induction of defensive innate immune responses against bacterial infection." (PMID 35439332, 2022). "Altogether, we hypothesize that the SARS-CoV-2 virus may mimic a bacterial infection via TLR4 and further CD64 dysregulation." (PMID 36460710, 2022). "Toll-like receptor 4 (TLR4) is an innate immune sensor for bacterial infection and tissue damage." (PMID 35359858, 2022). "Interestingly, TLR4-overexpression transgenic mice and sheep exhibited a survival advantage and improved bacterial phagocytosis during bacterial infection." (PMID 35370674, 2022). "Studies regarding TLR4 activation by bacterial infection in people living with HIV may shed light on how a TLR4 agonist can influence HIV evolution." (PMID 33919273, 2021). "Bacterial infection or LPS stimulation triggers assembly of the complex of Piezo1 and TLR4 to remodel F-actin organization and augment phagocytosis, mitochondrion-phagosomal ROS production and bacterial clearance and genetic deficiency of Piezo1 results in abrogation of these responses." (PMID 34112781, 2021). "However, fewer studies have focused on the response of pDCs against bacterial infection and the expression of TLR4 in the surface of pDCs, and on the effect of TLR4 ligands on pDC activation." (PMID 34603298, 2021). "Exploring the defence mechanism regulated by TLR4 may provide new targets for treatment of inflammation and control of bacterial infections." (PMID 33966642, 2021). "Several studies have focused on the function of TLR4 in bacterial infection." (PMID 33966642, 2021). "The expression of B2m, Ctsl, Calr, and Pdia3 suggests efficient antigen processing and presentation process, and the upregulation of Rac1, and Cd14 indicats the involvement of TLR2 and TLR4, which are essential for Th1/Th17 responses elicited by wPVs or bacterial infection." (PMID 34759909, 2021). "Activation of TLR4 signaling leads to the activation of NFkB and the transcription of proinflammatory cytokines, which are responsible for the acute phase response to bacterial infections." (PMID 35053195, 2021).
bacterial infection (continued). "In response to bacterial infection, the TLR4/MD-2 complex that is expressed on the surface of macrophages, monocytes, dendritic, and epithelial cells senses picomolar concentrations of endotoxic LPS and triggers the production of various pro-inflammatory mediators." (PMID 33329561, 2020). "Moreover, rSIP is an agonist of toll-like receptor 2 (TLR2) and TLR4, which suggests a dual role in the generation of innate and adaptive immune responses against bacterial infection." (PMID 32224855, 2020). "Our data demonstrate that TLR4 is significantly increased by increasing concentrations of LPS, suggesting that exosomes may facilitate some type of protective function against bacterial infection." (PMID 31547509, 2019). "Thus, the inflammation-related membrane proteins, TLR2 and TLR4, were selected as they play important roles in the immunity of bacterial infection." (PMID 31531116, 2019). "Since TLR4 is activated by LPS and other bacterial products, it is tempting to speculate that bacterial infections may, similarly to viruses, modulate airway epithelial cell repair occurring in response to injury induced by environmental factors." (PMID 30127243, 2018). "TLR4 plays a critical role in bacterial infections by recognizing lipopolysaccharide." (PMID 29368634, 2018). "In summary, our findings reveal previously unknown roles of c-Fos in the regulation of TLR-4 and IL-10 signaling, which are crucial for B. abortus internalization and growth in macrophages, suggesting a similar role for c-Fos in other bacterial infections." (PMID 30186773, 2018). "TLR4 is a critical driver of immune responses to bacterial infections." (PMID 29273011, 2017). "In addition, overexpression of DUSP12 in macrophages suppressed p38 and JNK activation in response to TLR4 stimulation or intracellular bacterial infection." (PMID 29062315, 2017). "Excessive stimulation of the TLR4 axis through LPS reduces the expression of somecytokine genes in immune cells, while stimulating the expression of immunedefense genes during a subsequent bacterial infection." (PMID 27913794, 2017). "Thus, we provide evidence of a novel mechanism of PKR activation requiring ER stress signalling that occurs as a consequence of TLR4 stimulation during bacterial infection and contributes to inflammatory responses." (PMID 27021640, 2016). "TLR4 is present in many compartments of the gestational tissues and reproductive tract and is well-positioned as a key sensing system and rapid first-line response to ascending or systemic bacterial infection." (PMID 27819333, 2016). "In bacterial infection, lipopolysaccharide (LPS) has been shown to interact with toll-like receptor 4 (TLR4) of dendritic cells (DCs) and induce NKT cell activation in the absence of an activating bacterial antigen, but is dependent on the secretion of IL-12 by DC." (PMID 25904903, 2015). "However, the transfection of AGS cells with TLR4 siRNA followed by the bacterial infection suppressed the expression of this receptor." (PMID 25873761, 2015). "In addition, it was found that the expression of MyD88, TRAF6 and TAK1 molecules are involved in the mechanism of TLR4 in human endometrial endothelial cell responses to bacterial infection." (PMID 25371751, 2014). "The TLR4-mediated immune response is the first line of defense against bacterial infection." (PMID 24025421, 2013). "Therefore, it is conceivable that altered epithelial TLR4-mediated chemokine production caused by CsA, may potentiate the deleterious inhibitory effects of CsA on Nod1-mediated neutrophil functions, leading to a more pronounced decrease in host resistance to bacterial infection." (PMID 23382681, 2013). "Therefore, in the case of bacterial infection, iNKT cells are activated not only via TLR4-mediated iNKT cell activation pathways that occur during tissue injury but also via direct recognition of bacterial glycolipids using the TCR." (PMID 23028952, 2012).
bacterial infection (continued). "Several studies have highlighted the importance of TLR4 in a number of bacterial infections." (PMID 21738466, 2011). "Expression of p30 in human macrophages (i.e., the THP-1 cell line) alters TLR4 signaling, a critical pathway in the innate response to bacterial infection, and inhibits the production of pro-inflammatory cytokines normally secreted in response to TLR4 stimulation." (PMID 21994785, 2011). "Moreover, it cannot be excluded that increased LPS release into the blood circulation due to secondary bacterial infection and/or increased gut permeability contributes to TLR4-dependent Tip-DC maturation during trypanosome infection." (PMID 20714353, 2010). "Furthermore, it is clear that TLR4 on endometrial epithelial and stromal cells plays an important role in the response to bacterial infection of the uterus and the development of PID." (PMID 20169203, 2010). "Other studies have looked at the role of TLR4 in mechanical ventilation; however, these studies have also used concurrent LPS administration or bacterial infection, making it difficult to separate out the contribution of mechanical ventilation on TLR4-dependent signaling." (PMID 21092115, 2010). "Moreover, while TLR4 remained up-regulated upon LPS treatment, TREM2 was downregulated, suggesting that LPS–TLR4 interaction during bacterial infections could down-regulate the anti-inflammatory action of TREM2." (PMID 38299364, 2024). "Besides immunological implications, the LPS binding of TLR4 on trigeminal neurons was shown to increase sensitization of TRPV1 channels, leading to increased expression of CGRP, which suggests a possible mechanism for pain associated with bacterial infections." (PMID 37627258, 2023). "Although TLR-4 is not considered directly responsive to gram-positive infections, several studies have emphasised its association with the inflammatory response to different bacterial infections, including those related to gram-positive staphylococci." (PMID 36440291, 2022). "Therefore, we analyzed the effect of the newly identified TLR4 antagonist on the cytokine response in human peripheral blood mononuclear cells (PBMCs) and in human whole blood in the presence of LPS as activating molecule, mimicking bacterial infection." (PMID 35208698, 2022). "Moreover, this research mimicked inflammatory response to bacterial infection in vitro by stimulating human macrophages with LPS, a strong stimulant specific to Toll-like receptor-4 (TLR4), to induce NF-κB-dependent proinflammatory genes and cytokines expressions." (PMID 34685815, 2021). "Furthermore, lipopolysaccharide-induced TLR4 signaling cascades were shown to repress the expression of the let-7 family and rescue cytokine production of IL-6 and IL-10, both of which are critical in bacterial infection." (PMID 33805523, 2021). "The aim of this study was to investigate, for the first time, whether the exposure of mast cells to A. baumannii components affects the expression of pro-inflammatory cytokines, chemokines, leukotriene synthase, and Toll-like receptor 4 (TLR4) during bacterial infection in vitro." (PMID 33802578, 2021). "According to our results, instead of effective bacterial clearance, bacterial infection in the peritoneal cavity was exaggerated for the bacteria in Group B (Lactobacillaceae, Erysipelotrichaceae, Clostridiaceae, and Enterobacteriaceae); however, the knockout of Tlr4 enhanced bacterial clearance." (PMID 31348811, 2019). "This suggests that some negative effects of bacterial infection on the hypothalamic-pituitary-gonadal axis activity at the hypothalamic level may be caused by central action of LPS acting through TLR4." (PMID 30026944, 2018). "Thus, the increase of the combined response to TLR3 and TLR4 suggests that there may be a specific effect of combined viral and bacterial infection on peripheral dysfunction of the lung during allergic conditions." (PMID 26494305, 2015).
bacterial infection (continued). "Our results showed that TLR2 and TLR4 expression by BMDMs controlled the potential response to microbial ligands and that this response was dramatically enhanced by GM-CSF priming, suggesting that GM-CSF can modulate the activation of macrophages in the host defense against bacterial infection." (PMID 22808181, 2012). "The expression of TRLs in the urothelial cells plays a key role in immune response against UTIs, with TLR2, TLR4, and TLR5 considered to be most important in bacterial infections." (PMID 41596750, 2026). "Toll-like Receptor 4 (TLR4) represents an essential receptor for recognizing LPS, which plays a critical role in the host’s immune response to bacterial infection." (PMID 40692792, 2025). "Studies examining the impact of bacterial infections on sperm quality have utilized TLR agonists, such as Pam3Cys (a TLR2 agonist) and lipopolysaccharide (LPS, a TLR4 agonist) in experimental settings." (PMID 40242391, 2025). "Looking at broader bacterial infection pathways such as Toll-like receptor signaling, we observed TLR2 and TLR4 upregulation in Mcat-infected samples and NTHi-infected samples with Mcat apical fluid, likely triggered by Mcat surface LOS or lipoproteins." (PMID 40492732, 2025). "Several innate immune signaling pathways are activated during bacterial infection, including Toll-like receptors (e.g.CD14/TLR4) and Nod-like receptors." (PMID 40114913, 2025). "Through the TLR4/TRPC1/NF-κB signaling pathway, TRPC1 has also been shown to contribute to the inflammatory response to bacterial infection." (PMID 40533673, 2025). "They assessed several SNPs of TLR4 and TLR9 genes with respect to different phenotypes such as bacterial infection, gingival inflammation/recession, and OSCC." (PMID 38606218, 2024). "In this study, we show that GBS HylB mediates immune suppression and promotes bacterial infection during pregnancy that requires TLR2, TLR4, and IL-10." (PMID 37747229, 2023). "LPS induces its neuroinflammatory response in mammals by binding to toll-like receptor 4 (TLR-4), which is a pattern recognition receptor (PRR) that is a critical immune response driver to bacterial infections." (PMID 36551844, 2022). "Our results showed that the expression levels of TLR4, TLR5, and MyD88 mRNA in the bladder epithelial cells were upregulated in response to the bacterial infection." (PMID 36506014, 2022). "We aimed to evaluate the expression of TLR4 and TLR5 genes in IPEC-J2 cells, as epithelial TLR expression appears to be key in the host defense against bacterial infection." (PMID 36556320, 2022). "It is well established that Toll-like receptors (TLRs), particularly surface TLRs such as TLR2, TLR4, and TLR5, play an essential role in defending against this bacterial infection." (PMID 36194127, 2022). "LY96 (Lymphocyte antigen 96), also known as MD-2 (Myeloid Differentiation factor 2), is a molecular chaperone of TLR4 (Toll-like receptor 4); the TLR4/MD-2 complex was found to control the early immune responses against bacterial infection." (PMID 35767190, 2022). "Upon bacterial infection, WRS is secreted by the monocytes, and directly binds to macrophages via a toll-like receptor 4 (TLR4)-myeloid differentiation factor 2 (MD2) complex, inducing phagocytosis and chemokine production." (PMID 36017335, 2022). "TLR4 and its co-receptors MD2 and CD14 are required for immune response to fungal and bacterial infection by recognition of microbial cell wall components, making it a prime target for drug development." (PMID 35208698, 2022). "Future studies will need to determine if S1PR2 can co-localize with TLR4, MyD88, RANK, TRAF6, MAPKs, PI3K, Src, and integrins in lipid rafts in response to bacterial infection or RANKL stimulation." (PMID 30609675, 2019). "Total mRNA was isolated from the prASCs in passage 2 cultured in standard medium to determine the constitutive expression of the relevant receptors for the bacterial infections (TLR-2 for LTA and TLR-4 for LPS)." (PMID 31671899, 2019).
bacterial infection (continued). "The GTPase RAB11A is involved in recruitment of TLR4 to phagosomes and IRF3 signaling, both of which are key events in the innate immune response and host defenses against bacterial infection and are highly relevant for IBD." (PMID 25927528, 2015). "For example, during a bacterial infection, the host’s pattern recognition receptor (PRR), toll-like receptor 4 (TLR4), is able to detect bacterial lipopolysaccharide (LPS) as a foreign pathogen-associated molecular pattern (PAMP)." (PMID 26337043, 2015). "In addition to its regulatory role in the expression of S100A9 and lipocalin-2 as we reported here, whether IL22 also contributes to urothelium defense mechanisms against bacterial infection by regulating HUC production of HA or HUC expression of TLR4/CD14 remains to be elucidated." (PMID 25354343, 2014). "Especially important for bacterial infections are TLR2, TLR4 and TLR9: TLR2 is activated by bacterial lipopeptides, TLR4 recognizes endotoxin (LPS) and pneumolysin (an important pathogenic factor of S. pneumoniae), and TLR9 is activated by bacterial DNA." (PMID 25528768, 2014). "Thus, CD44/HA and TLR4/CD14 could collaborate to diminish bacterial infection." (PMID 25354343, 2014). "Upon bacterial infection, splenic neutrophils and Ly6G+ CD11b+ myeloid cells from burn mice had significantly reduced TLR2, TLR4 and TLR5 expression compared to uninfected burn and infected sham mice." (PMID 24454904, 2014). "TLR4 and TLR9 recognise products of bacterial infection and little is known about human primary BEC IFN responses to TLR4 and TLR9 ligands in normal healthy subjects or in asthmatic subjects." (PMID 23824215, 2013). "For example, MyD88 adaptor-like (Mal) acts to bridge MyD88 to TLR4 or TLR2 complex and is capable of mediating NF-kB activation in response to bacterial infection." (PMID 24278275, 2013). "KLA is the active component of inflammatory lipopolysaccharide which functions as a selective agonist of Toll-like receptor 4 (TLR4) and mimics bacterial infection." (PMID 21303545, 2011). "Consistent with the data presented in this study, TLR-4 signaling and activated macrophages are capable of producing and responding to IL-1β and TNF-α to fight against bacterial infection." (PMID 20565713, 2010). "In healthy individuals, anaerobe abundance in bronchoalveolar lavage fluid correlates with expression of pro-inflammatory cytokines, elevated Th17 lymphocytes, and a blunted toll-like receptor 4 (TLR4) response, implicating a compromised first line of defense against bacterial infection." (PMID 40366160, 2025). "In the process of bacterial infection, the main component of the outer membrane of Gram-negative bacteria, LPS, can activate TLR4, triggering pro-inflammatory response transmission and promoting the body’s clearance of bacteria." (PMID 38885061, 2024). "Thus, G-CSF plays a key role in regulating granulopoiesis during bacterial infection, and TLR2 and TLR4 are essential to the host defense mechanism." (PMID 33763386, 2021). "The simultaneously and highly enhanced expressions of TLR4 and CD14 in PBMCs of pigs co-infected with PRRSV and PCV2 might render the animal vulnerable to secondary bacterial infection observed in the field." (PMID 29157279, 2017). "Recognition of LPS, a major component of the outer membrane of Gram-negative bacteria, by the TLR4/MD-2 complex is essential for the host’s ability to control bacterial infection." (PMID 29321776, 2017). "Mechanistically, PKCtheta exerts a host-protective role against S. typhimurium infection, and acts as an essential link between TLR4/IFNgammaR signaling and selective suppression of the anti-inflammatory cytokine IL-10 at the onset of CAM differentiation in the course of a bacterial infection." (PMID 27465248, 2016). "We hypothesize that, as in UDD bacterial infections are more frequent, lymphocytes expressing TLR2 and TLR4 are already mobilized and ready to mount the immune-response." (PMID 25133198, 2014).